CD4 (CD4 molecule)
Diseases named in the same sentence as CD4 in open-access papers (continued):
Sharing a sentence is not in itself a finding about the gene and the disease.
endometrial cancer (26 papers, 2012 to 2025). Primary or metastatic malignant neoplasm involving the endometrium (mucous membrane that lines the endometrial cavity). "Pearson correlation analysis results revealed that CKS2 expression was negatively linked with the infiltration level of B cell and CD4+ T cell in endometrial carcinoma (r = −0.125, p = 0.034; r = −0.173, p = 0.003)." (PMID 35693634, 2022). "Evidence in support of this theory is the observation that tumor infiltrating and peritumoral lymphocytes are increased and that cytotoxic activities in CD8+ and CD4+ lymphocyte populations are heightened in POLE mutated endometrial cancers, similar to hypermutated MSI tumors." (PMID 32838755, 2020). "In endometrial carcinoma, the CD4+/CD8+ TILs ratio has been reported to be significantly associated with expression of immune checkpoint proteins such as cytotoxic T-lymphocyte associated protein 4(CTLA-4) and PD-L1." (PMID 37974194, 2023). "Significant links were found between CKS2 expression and the infiltration level of B cells, CD4+ T cells, and neutrophils in endometrial carcinoma." (PMID 35693634, 2022). "The increased infiltration level of immune cells, including B cell, CD4+T cell, neutrophil, and dendritic cells as well as increased expression of ACE2 has been correlated with SARS-CoV-2 susceptibility in endometrial cancer." (PMID 33752656, 2021). "We have previously focused on antitumor immunity in the microenvironment of endometrial cancer, and reported that high density of CD4+ tumor-infiltrating immune cells (TICs) was a significant and independent prognostic factor for favorable overall survival in endometrial cancers." (PMID 39232704, 2024). "A recent study proved that microsatellite‐unstable endometrial cancer is characterized by the infiltration of B cells, CD4+ T cells, neutrophils and dendritic cells, which may affect the therapeutic effect and survival time." (PMID 35218676, 2022). "All these findings are consistent with the literature as CD4, CD8, FoxP3, and PD1 are inflammation markers, and POLE-mutated endometrial carcinomas, usually with a better prognosis than POLE WT, with higher abundance of A1 areas, are described to have large lymphocyte populations." (PMID 35217454, 2022). "In contrast, the percentage of CD4+ T cells increased in endometrial carcinomas." (PMID 33968059, 2021). "We assumed that upregulated CKS2 might reshape the tumor microenvironment of endometrial carcinoma by means of inhibiting the population of B cells and CD4+ T cells or increasing the population of neutrophils to contribute to the initiation and progression of endometrial carcinoma." (PMID 35693634, 2022). "In endometrial cancer, BUB1B expression was found to be relevant to the infiltration of activated CD4 + T cells and CD8 + T cells." (PMID 41163302, 2025). "In other panels, CD25++ CD45RA+CD4+ T cell, CD28- CD8+ T cell, CCR7 on naive CD8+ T cell, myeloid Dendritic Cell, Natural Killer cell, Basophil cell had positive links with endometrial cancer." (PMID 38746677, 2024). "A study on endometrial cancer reported that the CTSW gene had a positive correlation with tumor infiltration levels of B cells, CD8 + T cells, CD4 + T cells, macrophages, and dendritic cells." (PMID 37794108, 2023). "With regard to the correlation between CKS2 expression and the infiltration level of immune cells in endometrial carcinoma, significant bonds were observed between CKS2 expression and the immune infiltration of B cells, CD4+ T cells, or neutrophils." (PMID 35693634, 2022). "Endometrial carcinomas have a significantly greater number of total mixed, CD45+, CD3+, CD4+CD3+, and CD8+CD3+ cells per gram of tissue compared to adjacent non-cancerous tissue." (PMID 33968059, 2021).
endometrial cancer (continued). "The current findings indicate that PD-L1 and CD4+ helper T cells may be reasonable targets for improving survival through manipulating chemosensitivity, providing significant implications for combining immunotherapies into the therapeutic strategy for endometrial carcinoma." (PMID 32066405, 2020). "We performed immunohistochemistry of the TME proteins, PD-L1, PD-1, CD4, CD8, CD68, and VEGF in endometrial carcinomas from 221 patients." (PMID 32066405, 2020). "The current findings indicate that PD-L1 and CD4+ helper T cells may be reasonable targets for improving survival via enhancing chemosensitivity, providing useful information for combining immunotherapies into the therapeutic strategy for endometrial carcinoma." (PMID 32066405, 2020). "Similarly, more CD4+ T cells and CD8+ T cells were also observed in the POL&PBRM1 group in endometrial cancer." (PMID 39218995, 2024). "The results suggested that activated CD4+ T cell, effector memory CD4+ T cell, memory B cell and type 2 T helper cell may participate in the high TARS expression related immune response in endometrial cancer." (PMID 36881401, 2023). "Activated CD4+ T cell, effector memory CD4+ T cell, memory B cell and type 2 T helper cell may participate in the high TARS expression related immune response in endometrial cancer." (PMID 36881401, 2023). "Our results provide evidence for the differential distribution of CD4 and CD8 T cells in endometrium carcinoma immune microenvironment, and the increase of Treg and reduction of cytotoxic and naive cells may be characteristics of EEC." (PMID 36273006, 2022). "Increased numbers of CD4+ and CD8+ T cells could be due to the increased concentration of T cell chemokines such as RANTES present in endometrial carcinoma secretions and may reflect the efforts of the host immune system to restrict tumor growth." (PMID 33968059, 2021). "We report that endometrial carcinomas are enriched for immune cells with significantly greater numbers of both CD4+ and CD8+ T cells than that seen in adjacent non-cancerous endometrium." (PMID 33968059, 2021). "CD4, EPO, SOS1 and IFNA1 are related to several cellular mechanisms such as hematopoietic cell lineage determination, gonadotropin-releasing hormone (GnRH) signaling, cytokine-cytokine receptor interactions and endometrial cancer." (PMID 27832168, 2016).
fibrosarcoma (26 papers, 2010 to 2025). A malignant mesenchymal fibroblastic neoplasm affecting the soft tissue and bone. "FDX1 expression was found to be positively correlated with the percentage of CD8+ T cells and CD4+ T cells in fibrosarcoma." (PMID 38938647, 2024). "Selective accumulation in the tumors of CD4+ T cells (subpopulation of Tregs) was described for murine fibrosarcomas." (PMID 36612231, 2022). "In this model, DACT treatment alone sufficed to cure 5 out of 8 mice from transplanted fibrosarcoma, an effect which was completely abolished when CD4+ and CD8+ T cells were depleted with specific antibodies." (PMID 32323922, 2020). "AGE was shown to enhance the in vitro production of interferon-γ in splenocytes and increase the ratio of CD4+/CD8+ on implanted fibrosarcoma tumors in BALB/c mice, which improved the immune responses of mice to fibrosarcoma and inhibited tumor growth." (PMID 31284512, 2019). "IL-12 GET additionally increases the infiltration of immune cells into fibrosarcoma tumors and specifically of CD4+ and CD8+ T cells into murine melanoma tumors." (PMID 28596641, 2017). "In the study described herein, we conducted a broad analysis of chemokine expression by MCA-induced fibrosarcomas and a side-by-side analysis of Foxp3+ and Foxp3− CD4+ T cells in terms of their phenotype and migratory capacity." (PMID 25495686, 2015). "Our data were concordant with a recent study showing the administration of anti-TIM-3 mAb had a tumor-suppressing effect in several transplantable and chemical carcinogen-induced fibrosarcoma tumor models via CD4+ and CD8+ T-cell- and IFN-γ-dependent mechanisms." (PMID 24044888, 2013). "For instance, CD4+CD25+ Treg cells enhance susceptibility to 3-methylcholanthrene (MCA)-induced-tumorigenesis and depletion of CD4+CD25+ Treg cells reduced tumor growth of MCA-induced fibrosarcomas." (PMID 21943203, 2011). "Therefore, having established the chemokine profile of the fibrosarcomas under study, we next sought to quantify the proportions of tumour-infiltrating CD4+ T cells (both Foxp3+ and Foxp3−) that expressed the corresponding chemokine receptors for these chemokines." (PMID 25495686, 2015). "CD4-cre x IKKβfl/fl mice and littermate controls (CD4-cre x IKKβ+/fl) were subcutaneously injected with 106 MC57-SIY tumor cells, a mouse fibrosarcoma cell line engineered to express the model peptide antigen SIYRYYGL (SIY)." (PMID 25648675, 2015). "In a mouse model of fibrosarcoma, treatment with immune checkpoint inhibitors, (anti-PD-1 and -CTLA-4) induced the frequency and maturation of TA-HEVs and led to increased numbers of infiltrating CD4 and CD8 T cells." (PMID 38812785, 2024). "Also, we generated a new mouse strain, namely the Suv39h1-Flox*CD4-Cre, in which mice are KO for SUV39h1 only in T cells (see the section “Methods” for strain description), and we grafted them with the MCA-101 fibrosarcoma cell line, which is less immunogenic that the B16-F10-OVA." (PMID 35768432, 2022).
follicular lymphoma (26 papers, 2016 to 2025). Follicular lymphoma is a form of non-Hodgkin lymphoma characterized by a proliferation of B cells whose nodular structure of follicular architecture is preserved. "In the BM in particular, but in blood and lymph nodes an increase in the CD4/CD8 ratio has been associated with greater risk of BM involvement as well as worse clinical patient outcomes in follicular lymphoma." (PMID 33245727, 2020). "This study demonstrated that higher expression of positive CD4 cells predicts lower risk of early failure in follicular lymphoma, and combination analysis of CD4 and FLIPI could better predict disease relapse and survival outcome." (PMID 39248131, 2024). "defined an immune clinical prognostic index for newly diagnosed follicular lymphoma patients receiving R-CHOP chemotherapy, where blood CD4+ and CD8+ T cell counts were closely associated with patient prognosis." (PMID 41244913, 2025). "Previous results about prognostic value of CD4+ T cells in follicular lymphoma (FL) remain controversial." (PMID 39248131, 2024). "The expression, intensity, and distribution of positive CD4 cells in 103 follicular lymphoma patients." (PMID 39248131, 2024). "LINC00892 is induced by T cell activation and expressed in CD4+ T helper and follicular lymphoma T helper cells." (PMID 37346034, 2023). "It was highly expressed on CD4+ or CD8+ T cells with reduced function at the microenvironment in adult follicular lymphoma (FL)." (PMID 35992809, 2022). "In situ analyses of LINC00892 expression in normal lymph nodes and in follicular lymphoma biopsies show that its expression is limited to CD4+ PD1hi T cells, with a subcellular localization within the germinal center matching that of follicular helper T cells." (PMID 35736637, 2022). "In contrast, TIGIT is highly expressed on effector memory (around 80%), effector (around 50%) and central memory (around 40%) CD4+ T cells in follicular lymphoma patients." (PMID 34367161, 2021). "Increased numbers of intra-tumoral TIGIT+CD4+ and CD8+ T cells are associated with inferior patient outcomes and poor survival in follicular lymphoma patients." (PMID 34367161, 2021). "Infiltrating CD4+ T-cell subsets have been studied by others in follicular lymphoma and the distribution of cells in relation to the follicle associates with clinical characteristics." (PMID 30219078, 2018). "First, we examined GSE65135 microarray dataset which contains 14 follicular lymphoma samples consisting of CD4+ T cells, CD8+ T cells and B cells, with proportions estimated based on flow cytometry data." (PMID 30404611, 2018). "In addition, naïve B cells and follicular lymphoma B cells have been shown to induce the conversion of CD4+ T cells to Treg in a cell–cell contact manner, which potentially contributed to the increased signal of Treg observed in the TCGA transcriptomic data." (PMID 36853169, 2023). "In addition, CD4+PD1hi follicular lymphoma TILs lost their cytokine responsiveness, whereas PD-1neg TILs had normal cytokine signaling." (PMID 37741983, 2023). "To tackle the follicular nature of CD4+ T cells in the lymphoid aggregates, we performed IF stainings of CD4, CXCR5 together with NFATc1, again after having established detection on tonsils, follicular lymphoma of the spinal cord, and PCNSL of the brain." (PMID 32010141, 2019). "To investigate whether the inter‐follicular density of CD8+FOXP3+ and co‐localization of CD8+FOXP3+ with CD4+CD8+ are predictors of TTP independent of follicular lymphoma international prognostic index (FLIPI), we applied multivariate Cox regression analysis." (PMID 35451108, 2022). "However, another group claimed that increased numbers of CD4+ PD-1highTIM-3negative T cells in follicular lymphoma patients did not correlate to clinical outcome and that these cells were in fact still functional." (PMID 27379090, 2016).
Listeria monocytogenes infection (26 papers, 2010 to 2023). "Previously, our team demonstrated that ZEA and DON can inhibit the anti-listeria infection effect mediated by CD4 T cells in mice." (PMID 37298614, 2023). "Correspondingly, conditional deletion of FoxO4 in CD4+ T cells enhanced T cell–specific responses to Listeria monocytogenes infection in vivo." (PMID 36106640, 2022). "In this experimental study, listeriosis leading to rapid activation, proliferation and apoptosis of CD4 + and CD8 + T cells were revealed." (PMID 33862673, 2021). "In Listeria infection, previous work indicated that B10 cells inhibit CD4+ T cell expansion and bacterial clearance by macrophages through dampening the production of IFN-γ and TNF-α." (PMID 31474988, 2019). "In our listeria infection model, Il6rafl/fl×CD4cre and control mice showed similar frequencies of CD4+ and CD8+ T cells responding to stimulation with immunodominant peptides." (PMID 30169526, 2018). "In contrast, in experimental Listeria monocytogenes infection, the expression of IFNγ by CD4+ T cells was negatively regulated by IFNγR." (PMID 28671989, 2017). "Listeriosis patients with other co-morbidities presented better Th17 and CD4+ T cell immune responses." (PMID 27965668, 2016). "In this regard, DC or synthetic vaccines containing GADPH1–22 epitopes and targeted to DC seemed to confer protection against experimental listeriosis, promoting Th1-Th17 and CD4+-CD8+ T cell immune responses." (PMID 27965668, 2016). "Pathogen-specific CD8+ T cells play a major role in protection against listeriosis, but also pathogen-specific CD4+ T cells efficiently collaborate in conferring protective immunity." (PMID 24600592, 2014). "In this report, we show that for an endogenous polyclonal CD4+ T-cell population responding to Listeria infection, OX40 expression is induced during priming largely on responding antigen-specific T cells with an effector phenotype." (PMID 24771127, 2014). "This is believed to be the first study to explore the use of a novel GAPDH antigen as a potential DC-based vaccine candidate for listeriosis, whose efficiency appears to highlight the relevance of vaccine designs containing multiple CD4+ and CD8+ epitopes." (PMID 24600592, 2014). "To address this issue, we utilized LCMV and Listeria monocytogenes infection of mice to characterize primary and secondary antigen (Ag)-specific Th1 CD4 T cell responses." (PMID 23762323, 2013). "To determine whether the phenotypic difference in Listeria infection between WT and cKO mice was dependent on CD4+ T cells, we performed antibody-mediated depletion of CD4+ T cells during Listeria infection." (PMID 36106640, 2022). "CD4 depletion, however, did not reverse the bacterial burden, indicating that IL-17D exerts a pathogenic function during Listeria infection by repressing CD8 T cell activity." (PMID 31244826, 2019). "For example, Listeria monocytogenes infection-induced memory CD4 T cells are present at relatively high frequencies 90 days post-infection; however, by approximately 250 days post-infection, the population has largely disappeared from the spleen and lymph nodes." (PMID 25699040, 2015). "Therefore, primary T cell responses highlighted the role of L. monocytogenes-specific CD8+ T cells to confer significant protection against listeriosis, while CD4+ T cells seemed to participate less in protection." (PMID 24600592, 2014). "However, the CD4+-specific LLO189−201 epitope also confers protection against listeriosis and appears as the major epitope eluted from MHC-II molecules." (PMID 24600592, 2014). "However, KSR1-deficient mice displayed normal regulatory CD4+ T cell development, as well as normal memory CD8+ T cell responses to LCMV and Listeria monocytogenes infection." (PMID 23431403, 2013).
Listeria monocytogenes infection (continued). "Although assistance of CD4 T cells for the generation of CD8 T cell immune response is overruled during the primary immune response to Listeria monocytogenes infection, it plays centrestage for long term maintenance of memory CD8 T cells and establishment of protective immunity against reinfection." (PMID 24171157, 2013). "Likewise direct type I IFN action on CD4 T cells is important for clonal expansion in vivo following LCMV, but inhibitory during Listeria infection showing that the priming milieu determines the extent to which CD4 T cells are dependent on direct signal mediated by type I IFN." (PMID 26731269, 2016). "Interestingly, a very recent study highlights that a subunit vaccine that combines polyIC and an agonistic CD40 antibody could “program” protective CD4 independent CD8 T cell memory in response to Listeria monocytogenes infection." (PMID 24171157, 2013). "We previously showed that αDC-SIGN antibodies conjugated to OVA induce strong and persistent Ag-specific CD4+ and CD8+ T-cell responses which promote rapid clearance of OVA-expressing Listeria monocytogenes infection." (PMID 29662482, 2018). "We also described the features of the GAPDH1−22 peptide that contained CD8+-specific and CD4+-specific epitopes that were combined in DC vaccine vectors; DC-GAPDH1−22, confers protection against listeriosis with higher ratios than DC-LLO91−99 vectors." (PMID 24600592, 2014). "While Th17 CD4 T cells generated by intranasal Listeria infection (a Th1 pathogen) do not form memory cells, Candida and other fungal vaccines, as well as other conditions have been shown to induce Th17 memory cells in vivo." (PMID 25699040, 2015). "When the same number of purified SP3, SP4 thymocytes and naïve CD4+ T cells from C57BL/6 Ly5.1 mice were adoptively transferred into congenic Ly5.2 mice, similar levels of donor T cell activation were observed seven days after Listeria monocytogenes infection of the host." (PMID 22022412, 2011).